IL10 (interleukin 10)
Diseases named in the same sentence as IL10 in open-access papers (continued):
Sharing a sentence is not in itself a finding about the gene and the disease.
alveolitis (6 papers, 2005 to 2021). "IL-10-deficient mice exposed to Saccharopolyspora rectivirgula exhibited an increase in alveolitis associated with an upregulation of IFN-γ." (PMID 28427395, 2017). "In addition, IL-10 deficient mice treated with silica showed an intense alveolitis but a reduced fibrotic lung response compared to their wild-type counterparts." (PMID 16212659, 2005). "Moreover, using several mineral particles inducing different lung responses, we showed that IL-10 production in the lung of mice was up-regulated during the development of fibrosing alveolitis (FA, silica) but not in the resolutive alveolitis (RA, MnO2) or the non-inflammatory models (NI, WC)." (PMID 16212659, 2005).
anaplastic large cell lymphoma (6 papers, 2013 to 2021). Anaplastic large cell lymphoma (ALCL) is a rare and aggressive peripheral T-cell non-Hodgkin lymphoma, belonging to the group of CD30-positive lymphoproliferative disorders, which affects lymph nodes and extranodal sites. "Administration of the anti-IL-10 mAb showed also a remarkable protective effect, replicated in mice challenged with a different tumor, Anaplastic Large Cell Lymphoma." (PMID 23663506, 2013). "In addition to IL-10, IFN γ, IL-8, IL-17, IL-23, monocyte chemoattractant protein-1 and macrophage inflammatory protein-1β, and RANTES negatively also have negative effects on clinical prognosis in patients with ALK- anaplastic large cell lymphoma." (PMID 33154947, 2020).
benign prostatic hyperplasia (6 papers, 2014 to 2026). A non-cancerous nodular enlargement of the prostate gland. "Nuclear factor kappa B (NF-κB) subunits p65 and p50, along with the cytokines IL-18 and IL-10, are central mediators of inflammation, but remain understudied in the context of benign prostatic hyperplasia (BPH) and occupation-related risks." (PMID 41569207, 2026). "The current study also reports increased levels of IL-6, IL-10, IFN-γ, and IL-12p70 in Brazilian PCa patients, but those were compared to healthy controls, since prostate hyperplasia patients were not included." (PMID 40427694, 2025).
Brain atrophy (6 papers, 2012 to 2025). Partial or complete wasting (loss) of brain tissue that was once present. "Underlining the impact of IL-10 not only on the initial damage but also on the regeneration we found that Il10−/− mice showed significantly increased brain atrophy and worse neurological scores on day 14 when compared to littermate controls." (PMID 34772416, 2021). "One of these (IL-10) was also associated with brain atrophy in AD." (PMID 23762274, 2013).
bronchiectasis (6 papers, 2021 to 2024). Segmental, irreversible dilation of the bronchial tree resulting in the accumulation of secretions which leads to obstruction. "Compared to that of the controls, the levels of interleukin (IL)-6 (p<0.001), IL-10 (p<0.001), carbonylated proteins (p=0.001), and superoxide anions (p=0.046) were significantly increased in adults with bronchiectasis." (PMID 33886789, 2021). "The present study showed that compared to healthy controls, adults with bronchiectasis who were clinically stable presented increased levels of IL-6, IL-10, carbonylated proteins, and superoxide anion, and decreased catalase activity." (PMID 33886789, 2021). "In general, we speculate that the curative mechanisms of BMGLF in bronchiectasis are primarily associated with the expressional regulation of inflammatory factors such as IL6, IL10, MMP9, CXCL8, MAPK1, and ICAM1." (PMID 33488758, 2021). "IL-6 and IL-10 levels were increased in adults with bronchiectasis." (PMID 33886789, 2021). "In COPD patients, lower levels of IL-10 have been previously reported, suggesting that bronchiectasis is not influenced by this cytokine’s dysregulation typical of COPD disease." (PMID 36836801, 2023). "In a previous study, increased plasma levels of the immunomodulatory and anti-inflammatory cytokine IL-10 were found in adults with bronchiectasis compared to those without bronchiectasis." (PMID 36836801, 2023). "By mapping drug targets to disease targets, we identified 51 common targets, including IL10, TLR2, STAT3, IL6, and CXCL8, which served to indicate putative pathways whereby BMGLF could be used to treat bronchiectasis." (PMID 33488758, 2021). "Interestingly, increased plasma levels of the immunomodulatory and anti-inflammatory cytokine IL-10 were found in adults with bronchiectasis compared to those without bronchiectasis." (PMID 33886789, 2021).
cataract (6 papers, 2012 to 2024). Partial or complete opacity of the crystalline lens of one or both eyes that decreases visual acuity and eventually results in blindness. "The expression levels of IL-2, IL-4, IL-6, IL-10, IL-17A, and IFN-γ were analyzed in the AqH, and PHA-stimulation and non-PHA-stimulated cultures of PBMCs from these three types of cataract patients." (PMID 25303043, 2014). "We inferred that the expressions of IL-2, IL-4, IL-6, IL-10, IL-17A, and IFN-γ were the most likely to differ between inflammatory cataracts that are secondary to BD and VKH and AR cataracts." (PMID 25303043, 2014). "So, we focused in the present study on evaluation of selected pro-inflammatory cytokines (IL-1β, IL-6, IL-8, IL-17A, and TNF-α), anti-inflammatory cytokines (IL-4, IL-10, and IL-13), and the IL-1 receptor antagonist (IL-1Ra) in the aqueous humor of FECD and/or cataract eyes." (PMID 38792359, 2024). "The expressions of interleukin-2 (IL-2), IL-4, IL-6, IL-10, IL-17A, and interferon-γ (IFN-γ) were analyzed in aqueous humor (AqH), phytohemagglutinin (PHA)-stimulated and non-PHA-stimulated cultures of peripheral blood mononuclear cells (PBMCs) from the three types of cataract patients." (PMID 25303043, 2014).
cerebral edema (6 papers, 2015 to 2023). "Furthermore, treatment with 2′-FL maintained M2 microglial polarization through IL-4-induced STAT6 activation and IL-10 upregulation, which is crucial for the resolution of brain edema and recovery of motor behavior." (PMID 37372011, 2023). "In addition to elevated IL-10 and IL-17A, patients with gram-positive shunt infection had elevated levels of VEGF, a potent mediator of vascular permeability associated with cerebral edema and neutrophil migration in the CNS." (PMID 30626412, 2019). "Also, intravenously administered recombinant IL-10 reduced the level of cerebrospinal fluid pleocytosis, cerebral edema, and intracranial pressure in a rat model of pneumococcal meningoencephalitis." (PMID 25563481, 2015). "CCHF infection can cause endothelial cell dysfunction (with increased vascular permeability) through the induction of cytokines (tumor necrosis factor-α, interleukin-6, interleukin-10, interferon [IFN]-γ), which can result in cerebral edema." (PMID 25529825, 2015). "In our study, ICT treatment decreased the expression of IL-1β and TNF-α while increasing the level of IL-10, indicating that ICT inhibited neuroinflammation and cerebral edema induced by tMCAO in rats by decreasing proinflammatory cytokine levels and increasing anti-inflammatory cytokine levels." (PMID 36447154, 2022).
childhood asthma (6 papers, 2013 to 2023). "To address these discrepancies, we conducted a systematic review and meta‐analysis to assess the relationship between IL10 rs1800896 polymorphisms and the susceptibility to pediatric asthma." (PMID 37937689, 2023). "Modulation of the LMO2 and IL-10 CG methylation and/or their gene expression may provide a regimen for early prevention of PTS-associated childhood asthma." (PMID 31214241, 2019).
cholangiocarcinoma (6 papers, 2014 to 2025). A carcinoma that arises from the intrahepatic biliary tree (intrahepatic cholangiocarcinoma) or from the junction, or adjacent to the junction, of the right and left hepatic ducts (hilar cholangiocarcinoma). "In conclusion, IL-10-based regulatory cytokine networks evade host immune responses in cancer patients with IgG4-related diseases and further suggest an association with cholangiocarcinoma." (PMID 25132998, 2014). "In cholangiocellular carcinoma, the involvement of Treg and IL-10 in IgG4 induction has also been reported." (PMID 40563656, 2025). "Collectively, we focused the role of IL-10 in the crosstalk between M2 macrophages and intrahepatic cholangiocarcinoma cells." (PMID 33372604, 2020). "Elevated levels of cytokines and other bioactive molecules, including IL-10, TGF-β1, and matrix metalloproteinase-2 have been demonstrated to be highly associated with M2 polarization of macrophages that surround cholangiocarcinoma tumor cells." (PMID 30469416, 2018). "We describe two mechanisms where cholangiocarcinoma cells directly participate in the histogenesis of IgG4 reactions via cytokine milieu of IL-10." (PMID 25132998, 2014). "In conclusion, cholangiocarcinoma cells perform immunosuppressive functions similar to Treg cells via IL-10 production and possibly induce the differentiation of IgG4-positive plasma cells in biliary tract cancers." (PMID 25132998, 2014). "Therefore, in IgG4-SC, an IL-10-related cytokine milieu initiates the IgG4 reaction and also suppresses tumor-reactive T cells, suggesting that IgG4-SC may accelerate cholangiocarcinoma development." (PMID 25132998, 2014). "We found that macrophages stimulated with the supernatant of cholangiocarcinoma cells expressed high levels of M2 markers, including CD163, CD206, ARG-1, and IL-10." (PMID 39256888, 2024). "IL-10 concentration was significantly increased in the HCC, GBC, and cholangiocellular carcinoma groups." (PMID 29410961, 2017). "Therefore, this study provides significant contribution to the literature since it is the first study to report on increased IL-10 concentrations in GBC and cholangiocellular carcinoma." (PMID 29410961, 2017). "Cholangiocarcinoma cells are nonprofessional APCs and/or regulatory cells that directly induce IgG4 reactions in an IL-10-predominant cytokine milieu." (PMID 25132998, 2014). "Cholangiocarcinoma cells may function as nonprofessional antigen presenting cells that indirectly induce IgG4 reactions via the IL-10-producing cells and/or these may act as Foxp3-positive and IL-10-producing cells that directly induce IgG4 reactions." (PMID 25132998, 2014).
colon polyps (6 papers, 2016 to 2021). "In contrast, the ablation of IL-10 specifically in T cells produced pathologies like in systemic IL-10 deficient mice, increasing the number and growth of colon polyps." (PMID 32674255, 2020). "Depleting IL-10 resulted in a fivefold increase in colonic polyps and alterations to epithelial barrier integrity that enabled the expansion of pathogenic bacteria Bacteroides and Porphyromonas within colonic polyps compared to healthy mucosa." (PMID 34298598, 2021). "Recently, pre-cancerous colon polyps were shown to be enriched for IL-10 producing NKT cells." (PMID 32127556, 2020). "By contrast, colon polyps were not affected by IL10 deficiency and progressed in IL10 deficient mice with extensive infiltration of the polyps with CTMCs." (PMID 31849960, 2019). "However, colonic polyps were only observed in DSS-treated IL10−/− mice, and not in the DSS-treated IL10+/− mice." (PMID 32286276, 2020).
colorectal adenoma (6 papers, 2009 to 2025). An adenoma that arises from the colon or rectum. "Several studies have shown that, similar to CRCs, colorectal adenomas also display the presence of interleukin 10 (IL-10)-producing regulatory T cells and CXCL8 overexpression." (PMID 38979413, 2024). "The aims of this study were to examine whether serum concentrations of IL-1β, IL-2, IL-8, IL-10, IL-12p70, GMCSF, IFNγ, and TNFα were associated with flavonol intake or could predict colorectal adenoma recurrence." (PMID 20924374, 2010). "In addition, colorectal adenomas harvested from Il10−/− mice showed consistently increased Ki67 staining compared to normal mucosa." (PMID 19551144, 2009). "Colorectal adenomas, similar to CRC, have been found to contain and/or express interleukin 10 (IL-10)-producing regulatory T cells, along with an over-expression of CXCL8 (neutrophil-attracting inflammatory chemokine)." (PMID 40149674, 2025). "In the current study, we examined serum concentrations of eight cytokines (IL-1β, IL-2, IL-8, IL-10, IL-12p70, GMCSF, IFNγ, and TNFα) in relation to flavonol intake and colorectal adenoma recurrence and found none to be associated with flavonol intake and with colorectal adenoma recurrence." (PMID 20924374, 2010).
cystitis (6 papers, 2013 to 2023). Inflammation of the urinary bladder. "The underlying basis of the inability of the bladder to mount an adaptive response has been linked to increased local IL-10 production, as IL-10-deficient mice showed substantial antibody responses to bladder infection." (PMID 32821646, 2020). "To see if mast cells were the cellular source of IL-10 at the 6 h point after infection, we compared IL-10 expression in the bladders and kidneys of wild type and mast cell deficient (Wsh) mice following cystitis and pyelonephritis." (PMID 26907352, 2016). "In the CYP-induced rat cystitis model, multiplex analysis of cytokine levels also revealed increased inflammation-associated cytokines in the urine and bladder tissue, including IL-6, IL-1β, monocyte chemotactic protein-1, and IL-10." (PMID 24146927, 2013). "Cumulatively, these studies indicate the defective serological response to bladder infection is attributable to immune suppressive actions of mast cell mediated IL-10." (PMID 26907352, 2016). "ELISA for IL-10 in the urine of wild type mice and Wsh mice with bladder infections confirmed this finding." (PMID 26907352, 2016). "Employing mouse models of infection, we have linked the abrogation of the adaptive immune response following bladder infection to the abrupt production of anti-inflammatory cytokine IL-10 by local mast cells." (PMID 26907352, 2016). "Finally, to test the functional importance of B-cell derived IL10 on local bacterial clearance in vivo, we performed a UTI (cystitis model) in B-IL10-KO mice." (PMID 37925420, 2023). "Although these secretory cells have an important role in initiating a vigorous immune response in the early phases of bladder infection, mast cells seem to reverse their activity approximately 6 hours post-infection by switching to IL-10 production to shut down this response." (PMID 32821646, 2020). "Therefore, increase of IL-10 in the bladder upon infection influences the activation of lymph node draining dendritic cells and may explain the uniquely dampened antibody responses to bladder infection." (PMID 26907352, 2016). "We found mice reconstituted with wild type but not IL-10−/− derived mast cells evoked IL-10 responses following bladder infection." (PMID 26907352, 2016).
fracture (6 papers, 2013 to 2021). "In general, hip fracture induced remarkable cytokine (IL-6 and IL-10) release, miRNA (miR-146a and miR-150) abnormal expression, and ALI." (PMID 30510490, 2018). "To check the status of immune response associated with hip fractures, we determined the serum TNF-α and IL-10 levels as well as the serum TNF-α/IL-10 ratio in rats at 24, 48, or 72 h after the hip fracture." (PMID 29357879, 2018). "Dead or moribund rats with hip fracture exhibited significantly reduced TNF-α/IL-10 ratio compared with healthy controls and other hip fracture rats, which were therefore named as hip fracture rats with IMD." (PMID 29357879, 2018). "In order to determine if hip fracture surgery was associated with changes in serum cytokine levels, IL-6, TNF-α, IL-1β, and IL-10 levels in blood were quantified 1, 3, and 7 days after hip fracture and surgery (including sham-operated controls)." (PMID 24163505, 2013). "13.3% (6 of 45) of hip fracture rats were dead or became moribund at 72 h after hip fracture, and simultaneously, the serum TNF-α/IL-10 ratio in these rats was significantly downregulated compared with that in normal rats and other hip fracture rats." (PMID 29357879, 2018). "Our result showed that in elderly hip fracture rats, the serum levels of TNF-α and IL-10 were almost significantly increased compared with healthy controls, which was consistent with those previously reported." (PMID 29357879, 2018). "This study is aimed at examining the differential expression of miR-146a, miR-150, and cytokines (IL-6 and IL-10) between younger and elderly rats suffering from hip fracture and investigating the possible meaning of them in early diagnosis and prognosis of ALI after hip fracture." (PMID 30510490, 2018).
gastric adenocarcinoma (6 papers, 2013 to 2022). "Shokrzadeh and other authors reported that the serum IL-10 levels were significantly higher in the patients with gastric adenocarcinoma than in the healthy controls." (PMID 36009467, 2022). "In fact, it has been indicated that a lack of Il-10 allows induction of pro-inflammatory cytokines hampering anti-tumor immunity, and that an increased level might be used as diagnostic biomarker in certain cancer such as stomach adenocarcinoma." (PMID 31351482, 2019).
Helicobacter infection (6 papers, 2010 to 2021). "Thus mast cells do not affect the incidence of inflammation-associated neoplasia in Il10−/− mice with severe long-standing compromise of the mucosal barrier due to helicobacter infection." (PMID 20808919, 2010). "Therefore, we investigated the associations between IL10 polymorphisms, Helicobacter pylori (H. pylori) infection, and smoking in noncardia gastric carcinogenesis in Koreans." (PMID 22235320, 2012).
hip fracture (6 papers, 2013 to 2023). Traumatic or pathological injury to the hip in which the continuity of either the femoral head, femoral neck, intertrochanteric or subtrochanteric regions is broken. "In conclusion, the present study reports for the first time that development of new onset depressive symptoms in older hip fracture patients results in numerical and functional deficits in Bregs but an increase in IL10 production by CD4 T cells." (PMID 26112234, 2016). "In addition we also found impairments in immunosuppressive properties of these cells with age and here we show an additional decline in IL10 production upon CD3 stimulation in hip fracture patients with depressive symptoms." (PMID 26112234, 2016). "Interestingly, there was a significant association between GDS scores and the frequency of peripheral IL10+ CD4 T cells in hip fracture patients, β = .34, p = .04, ΔR2 = .11, such that hip fracture patients with greater depressive symptoms (GDS score) had a higher frequency of IL10+ CD4 T cells." (PMID 26112234, 2016). "Particularly, patients with hip fracture have significantly increased serum levels of inflammatory cytokines (e.g., TNF-α, IL-6, IL-10) compared with healthy controls." (PMID 29357879, 2018). "Bregs also showed a significant decline in IL10 production in depressed hip fracture patients compared with controls (p = 0.04) and non-depressed patients (p = 0.01)." (PMID 26112234, 2016). "These symptoms were associated with poorer neutrophil superoxide production and a higher cortisol:DHEAS ratio, as well as greater levels of the cytokines IL6 and TNFα and lower IL10, compared to healthy controls and hip fracture patients without depressive symptoms." (PMID 23876747, 2013).